PDCD4 (programmed cell death 4)
Diseases named in the same sentence as PDCD4 in open-access papers (continued):
Sharing a sentence is not in itself a finding about the gene and the disease.
pancreatic cancer (continued). "An elevated level of miR-21 was shown to promote drug resistance to 5-FU and enhance the proliferation of pancreatic cancer cells by downregulating the expression of its target genes PTEN and PDCD4." (PMID 38139352, 2023). "Most downregulated RBPs include PAIP2B, SIDT2, PDCD4, AZGP1, and RNASE1, among which we report for the first-time involvement of PAIP2B, SIDT2, PDCD4, and RNASE1 in pancreatic cancer." (PMID 34912796, 2021). "After confirming which clones did not express miR-21, we measured the basal expression of PDCD4 and BTG2 in three PANC-1 KO miR-21 clones (c4, c5 and c6), and compared it with the control pancreatic cancer cell line PANC-1 expressing high levels of miR-21." (PMID 29464088, 2018). "PDCD4, GPI, and BHLHE4 are proteins with a described role in pancreatic cancer and, consequently, information about factors that can modulate their expression is important." (PMID 29464088, 2018). "The most well-known one is miR-21, which is upregulated in pancreatic cancer and targets many apoptosis related genes including PTEN and PDCD4, resulting in inhibited apoptosis and consequently, increased tumorigenicity." (PMID 26338139, 2015). "Our work demonstrates that miR‐21 can confer drug resistance to 5‐FU in pancreatic cancer cells by regulating the expression of tumor suppressor genes, as the target genes of miR‐21, PTEN and PDCD4 can rescue 5‐FU sensitivity and the phenotypic characteristics disrupted by miR‐21." (PMID 26864640, 2016).
esophageal cancer (23 papers, 2010 to 2025). A primary or metastatic malignant neoplasm involving the esophagus. "Also, it was found that high expression of miR-21 and down-regulation of PDCD4 expression was associated with the aggressive progression and poor prognosis of stage II esophageal carcinoma." (PMID 34525952, 2021). "Upregulation of miR-183 by targeting PDCD4 inhibits apoptosis and enhance proliferation in esophageal cancer." (PMID 35402235, 2022). "The miRNA-21-induced decrease in PDCD4 can result in increased chemoresistance to cisplatin in oesophageal cancer cells and to fluorouracil (5-FU) in colon cancer cells." (PMID 35847932, 2022). "In esophageal cancer, exosome-mediated transferring of MiR-21 provokes cisplatin-resistant phenotype in recipient cells through targeting programmed cell death 4 (PDCD4) mRNA and downregulating its protein level." (PMID 33407894, 2021). "Crucially, a previous report concluded that miRNA-183 inhibits apoptosis and enhances proliferation in esophageal cancer by targeting PDCD4." (PMID 33653339, 2021). "Consistently, exosome-derived oncogenic miR-21 has also been shown to weaken DDP sensitivity of esophageal cancer cells by silencing programmed cell death 4 (PDCD4)." (PMID 34881242, 2021). "In esophageal carcinoma, down-regulation of miR-21 led to an increase in PDCD4 protein levels and a decrease in cellular proliferation and invasion." (PMID 20831814, 2010). "Upregulation of miR-21 by targeting PDCD4 could increase migration and invasion of the cell in esophageal cancer." (PMID 35402235, 2022). "It has been proved that PDCD4 is a target gene of miR-330-3p in human esophageal cancer." (PMID 33744861, 2021). "In addition, miR-21 affected the sensitivity of esophageal cancer to cisplatin through targeting programmed cell death 4 (PDCD4) gene." (PMID 34378676, 2021). "Additionally, miR-21 containing exosomes have been shown to promote migration and invasion of recipient esophageal cancer cells by targeting programmed cell death 4 (PDCD4) and activating the c-Jun N-terminal kinase (JNK) pathway." (PMID 27872688, 2017). "PDCD4 is one of the most frequently down-regulated proteins in esophageal cancer." (PMID 26918602, 2016). "In esophageal cancer, ISA can inhibit miR-21, which silences programmed cell death 4 (PDCD4) and promotes cell proliferation, resulting the unleashing of PDCD4 and cell death." (PMID 39376605, 2024). "In esophageal cancer, exosomal miR-21 promoted cell migration and invasion by targeting PDCD4 (programmed cell death 4) and activating its downstream c-Jun N-terminal kinase (JNK) signaling pathway." (PMID 31752198, 2019). "Together, these studies in esophageal cancer highlight miR-21’s multifaceted roles in regulating cell adhesion, immune responses, core oncogenic pathways like PI3K/Akt, and potentially radiosensitivity, often through established targets like PTEN and PDCD4." (PMID 41476448, 2025).
prostate carcinoma (21 papers, 2010 to 2024). A carcinoma that arises from epithelial cells of the prostate gland. "In summary, we found higher expression of miR-182 in an AA prostate cancer cell line and tissue samples compared to EA and miR-182 directly targets PDCD4 and is associated with aggressiveness in prostate cancer." (PMID 34525952, 2021). "Our results showed that PDCD4 is a direct miR-182 target and its inhibition is associated with aggressiveness and high Gleason grade in prostate cancer among AA." (PMID 34525952, 2021). "Collectively, our results show that PDCD4 is a direct miR-182 target and is associated with AA aggressiveness and high Gleason grade in prostate cancer." (PMID 34525952, 2021). "This suggests that the interaction of miR-182 and PDCD4 is associated with prostate cancer aggressiveness in AA patients." (PMID 34525952, 2021). "Down-regulation of PCAT29 was associated with increased STAT3 and decreased levels of PDCD4 (a downstream target of miR-21) in Grade 4 prostate cancer." (PMID 28467474, 2017). "Also, PDCD4 is a direct miR-182 target and its inhibition is associated with aggressiveness and high Gleason grade in prostate cancer among AA." (PMID 34525952, 2021). "Interestingly, we found that low PDCD4 expression is associated with higher Gleason grade suggesting that PDCD4 is associated with racial disparity and prostate cancer aggressiveness." (PMID 34525952, 2021). "Studies have shown that PDCD4 protein is predominantly localized in the cytoplasm, and that lower levels of PDCD4 expression are correlated with less differentiated prostate cancer." (PMID 39114567, 2024). "EF24 significantly downregulates miR-21 in prostate cancer cells, which causes an increase in PTEN and PDCD4 expression." (PMID 39445208, 2024). "Zhu et al35 showed that rs55829688 CC + rs145204276 del/del genotype had an impact on the prognosis and survival rate of prostate cancer patients through the regulation of miR‐21/miR‐1284 expression, which consequently affected PDCD4, PTEN and AKT expression." (PMID 33728802, 2021). "Immunolabeling for PDCD4 showed high expression of this protein in normal specimens, compared to lower levels of this protein in prostate cancer." (PMID 28467474, 2017). "This study provides experimental data to drive future efforts in prostate cancer gene therapy and diagnosis that are based on IL-6, miR-21, and PDCD4." (PMID 26252635, 2015). "There was a marked difference in the PDCD4 expression pattern among specimens of prostate cancer, prostatic intraepithelial neoplasia, and prostatic hyperplasia." (PMID 26252635, 2015). "Given that the expression levels of PDCD4 differ with the extent of disease in prostate tissues, PDCD4 can be a promising tumor marker for both the diagnosis and treatment of prostate cancer." (PMID 26252635, 2015). "PDCD4 protein expression increased after LNCaP and PC-3 cells were transfected with the miR-21 inhibitor (PC-3 cells: Z = −3.920, P < 0.001; LNCaP cells: Z = 3.883, P < 0.001), suggesting that PDCD4 is regulated by miR-21 in these prostate cancer cell lines." (PMID 26252635, 2015). "Results from PSA and PDCD4 staining in different prostate tissue types revealed that the less differentiated the prostate cancer, the lower the level of PDCD4 expression and the higher the level of PSA expression." (PMID 26252635, 2015). "In this study, we evaluated the role of IL-6 in PDCD4 gene expression and how the microRNA miR-21 regulates this process in prostate cancer cell lines PC-3 and LNCaP." (PMID 26252635, 2015). "The expression pattern of PDCD4 from samples from human prostate cancer, precancerous lesions, and benign prostatic hyperplasia was investigated by immunohistochemistry." (PMID 26252635, 2015). "Our studies show that miR-21 promotes the growth of prostate cancer cells by downregulating the expression of PDCD4." (PMID 26252635, 2015).
prostate carcinoma (continued). "Short interfering (si) RNA against PDCD4 attenuated resveratrol’s effect on prostate cancer cells, and similar effects were observed following over expression of miR-21 with pre-miR-21 oligonucleotides." (PMID 23272133, 2012). "Additionally, miR-21 has been found to enhance the growth of prostate cancer cells by reducing the expression of PDCD4." (PMID 39114567, 2024). "Additionally, resveratrol increased the expressions of tumor suppressors, PDCD4 and maspin, to reduce prostate cancer growth and metastasis by inhibiting the Akt/microRNA-21 pathway." (PMID 27409165, 2016). "Thus, our results suggest that the PDCD4 gene is the target of miR-21 regulation in prostate cancer." (PMID 26252635, 2015). "Also, IL-6 affects PDCD4 expression throughout the development of prostate cancer in both androgen-dependent prostate cancer and androgen-independent prostate cancer." (PMID 26252635, 2015). "Curcumin treatment could result in a >80% knockdown of miR-21 expression in prostate cancer cells, thus increasing expression of several downstream target genes, including PTEN and PDCD4, and inducing apoptosis in prostate cancer cells." (PMID 26305257, 2015). "In this study, we determined whether IL-6 regulates the expression of the PDCD4 gene and defined the role of miR-21 in this process in the prostate cancer cell lines LNCaP and PC-3." (PMID 26252635, 2015). "Our study also found that PDCD4 is a target of miR-21 regulation in prostate cancer cells." (PMID 26252635, 2015). "PDCD4 suppresses cell growth via a direct interaction with TWIST1 in human prostate cancer." (PMID 25144746, 2014). "MiR-21 contributed to the resistance of prostate cancer cells to docetaxel by targeting PDCD4." (PMID 24106980, 2013). "Accordingly, different pathways for regulating PDCD4 expression may be active in different prostate cancer cell lines." (PMID 23272133, 2012). "Moreover, a recent study conducted in prostate cancer cells suggested an increased cisplatin and paclitacel sensitivity by over-expression of PDCD4." (PMID 22272332, 2012). "Therefore, AR may be the common target for IL-6 and miR-21 in prostate cancer, with miR-21 playing an intermediary role in activating IL-6 to regulate PDCD4 expression." (PMID 26252635, 2015). "To determine whether miR-21 and PDCD4 expressions were different in androgen-dependent and androgen-independent prostate cancer, we performed our studies in the androgen-independent prostate cancer cell line PC-3 and the androgen-dependent prostate cancer cell line LNCaP." (PMID 26252635, 2015). "In prostate cancer cells, curcumin downregulates miR-21, leading to an increase in phosphatase and tensin homolog gene (PTEN) and programmed cell death protein 4 gene (PDCD4) (target genes for miR-21), and a decrease in proliferation markers such as cyclin D1." (PMID 39445208, 2024). "MiR-21 regulates prostate cancer progression by down-regulating tumor suppressor genes, such as PTEN and PDCD4." (PMID 28467474, 2017). "Knockdown of PDCD4 reduced the ability of resveratrol to mediate the growth and invasiveness of PC-3M-MM2 prostate cancer cells." (PMID 23272133, 2012). "In prostate cancer cell lines, down-regulation of miRNA-21 activity by antisense oligonucleotides also results in an increase in PDCD4 expression, but without a change in proliferation, possibly indicating that PDCD4 does not act as a tumour growth repressor in some cell types." (PMID 35847932, 2022). "Transforming growth factor, beta receptor 2 (TGFBR2), Programmed cell death protein 4 (PDCD4), Reversion-inducing cysteine-rich protein with kazal motifs (RECK), p57kip2 and Phosphatase and Tensin Homolog Deleted from Chromosome 10 (PTEN) have been reported as miR-21 targets in prostate cancer." (PMID 28783103, 2017). "In addition, we observed localization of PDCD4 mainly in nuclei of epithelial cells in normal but not in these cells in prostate cancer specimens." (PMID 28467474, 2017).
prostate carcinoma (continued). "The overexpression of PDCD4 has been reported to increase the sensitivity to CDDP and paclitaxel, but not to etoposide or 5-fluorouracil in human prostate cancer PC3 cells." (PMID 24348845, 2014). "However, depletion of miR-21 neither resulted in change in downstream targets like PDCD4 and PTEN, nor affected the response to paclitaxel in prostate cancer cells." (PMID 24106980, 2013).
myocardial infarction (19 papers, 2014 to 2025). Gross necrosis of the myocardium, as a result of interruption of the blood supply to the area, as in coronary thrombosis. "In another study, miR-145 overexpression protected rats from myocardial infarction by targeting PDCD4 and consequently reducing apoptosis and mitochondrial stress." (PMID 36553664, 2022). "Recent studies have confirmed that miR-145 can protect against rat myocardial infarction by targeting PDCD4." (PMID 35034587, 2022). "miRNA-21 (miR-21) shows promise in reducing myocardial infarct size and cardiomyocyte apoptosis during acute myocardial infarction, and aids cardiovascular regeneration by regulating target genes like programmed cell death 4 (PDCD4)." (PMID 40004206, 2025). "Additionally, MALAT1 has been reported to target miR-144-3p and thus contribute to apoptosis in myocardial infarction and affect cardiomyocyte apoptosis after hypoxia/reperfusion injury through modulation on miR-200a-3p/PDCD4." (PMID 36700468, 2022). "In a rat model of IRI, overexpression of miR-21 in the heart could reduce cardiomyocyte apoptosis and myocardial infarct size, as well as protect the myocardium from ischemia/reperfusion by inhibiting Pdcd4 transcription." (PMID 34917083, 2021). "It has been previously reported that miR-145 could protect against rat myocardial infarction by targeting PDCD4." (PMID 31085717, 2019). "In the rat model of I/RI, overexpression of miR-21 in the heart could reduce cardiomyocyte apoptosis and myocardial infarct size, as well as protect the myocardium from ischemia/reperfusion by inhibiting PDCD4 transcription." (PMID 30622671, 2018). "Additionally, a circular RNA, circPVT1, protects the myocardium from myocardial infarction (MI) and hypoxia/reoxygenation (H/R) injury by miR-125b/miR-200 sponges and then regulating Keap1/Nrf2- and Pdcd4-mediated apoptotic signaling." (PMID 34917083, 2021). "PDCD4 was found induced by H2O2 in cardiac myocytes, which suggests a role of PDCD4 in heart diseases such as myocardial infarction." (PMID 24626527, 2014).
atherosclerosis (17 papers, 2014 to 2023). A disease characterized by the build-up of fatty material and calcium deposition in the arterial wall resulting in partial or complete occlusion of the arterial lumen. "In this study, we generated an animal model of atherosclerosis by raising apolipoprotein E-deficient (ApoE−/−) mice on a high-fat diet and investigated the expression of miRNA-21 and its target PDCD4 during the progression of atherosclerosis in these animals." (PMID 31886257, 2019). "Taken together, these data indicated deficiency of Pdcd4 in hematogenous cells contributed to the attenuation of atherosclerosis plaque formation." (PMID 26775706, 2016). "Dysregulated PDCD4 concentrations have also been reported to underlie a variety of metabolic disorders, including polycystic ovary syndrome, obesity, diabetes, and atherosclerosis, highlighting the critical role PDCD4 plays in regulating gene expression in multiple cell types." (PMID 34617965, 2021). "Importantly, Pdcd4 deficiency enhanced macrophage lipoautophagy and attenuated macrophage foam cell formation and atherosclerosis." (PMID 26775706, 2016). "Our recent study of PDCD4 and ApoE double-deficient mice (PDCD4−/−ApoE−/−) fed a high-cholesterol diet found that knockout of PDCD4 was associated with reduced atherosclerosis plaque areas (unpublished data), so PDCD4 downregulation might protect arteries against atherosclerosis." (PMID 24626527, 2014). "Specifically, miR-16 directly targets PDCD4, leading to the suppression of inflammatory macrophage activation in atherosclerosis through pathways such as MAPK and NF-κB, as well as downstream inflammatory cytokines." (PMID 38140218, 2023). "MiR-16 is reported to target PDCD4 to suppress macrophage pro-inflammatory polarization in atherosclerosis." (PMID 36153633, 2022). "PDCD4 is involved in atherosclerosis pathology probably through enhancing levels of IL-6 and IL-8 and promoting apoptosis of VSMC in animal models of coronary atherosclerosis." (PMID 32599769, 2020). "In conclusion, we investigated the expression of miRNA-21 and its target PDCD4 during disease progression in an ApoE−/− mouse model of atherosclerosis induced by a high-fat diet." (PMID 31886257, 2019). "Bone marrow transplantation experiment demonstrated that PDCD4-mediated autophagy in hematopoietic cells contributed to the development of atherosclerosis." (PMID 26775706, 2016). "Previous studies reveal that knocked down PDCD4 played an important role in attenuating foam cell formation and atherosclerosis in ApoE−/− mice." (PMID 27843203, 2016). "Taken together, our analysis of Pdcd4-deficient mice and foam cell formation demonstrated the important role of PDCD4 on regulation of autophagy-dependent cholesterol efflux, foam cell formation and atherosclerosis." (PMID 26775706, 2016). "Upregulation of miR-16 by targeting PDCD4 could inhibit inflammatory macrophages activation in atherosclerosis through the MAPK and NF-κB pathways." (PMID 35402235, 2022). "In conclusion, our results suggest that WWP2 protects against atherosclerosis progression via the PDCD4/HO-1 pathway, which may provide a novel treatment strategy for atherosclerosis." (PMID 35983977, 2022). "In atherosclerosis, PDCD4, as a target of miR-16, may inhibit the activation of inflammatory macrophages via the mitogen-activated protein kinase (MAPK) and NF-κB and signaling pathways, suggesting that PDCD4 could be a focus of atherosclerosis therapy." (PMID 31886257, 2019). "Therefore, clarification of the role of miRNA-21 (and other miRNAs) and its target PDCD4 in atherosclerosis is urgently needed." (PMID 31886257, 2019). "Our data suggest that promoting macrophage autophagy through downregulating PDCD4 expression may be beneficial in atherosclerosis-related diseases." (PMID 26775706, 2016). "PDCD4 downregulation may be important in protecting aortas against atherosclerosis." (PMID 24626527, 2014).
atherosclerosis (continued). "Recent studies have found that PDCD4 negatively regulates autophagy by inhibiting the expression of ATG5 in tumour cells and plays a certain role in autophagy in the treatment of atherosclerosis." (PMID 37461031, 2023). "Pdcd4 (programmed cell death 4) may suppress the activation of inflammatory macrophages via NF-kB and mitogen-activated protein kinase (MAPK) signaling in atherosclerosis." (PMID 36991462, 2023). "Increasing evidence supported that PDCD4 plays a negative role in the progression of atherosclerosis." (PMID 35983977, 2022). "On the other hand, in a recent study on the tumor-supressor gene programmed cell death 4 (PDCD4), it was demonstrated that the protein inhibited autophagy in macrophages, and Pdcd4 knockout mice displayed increased atherosclerosis, indicating a link between autophagy and atherogenesis." (PMID 28662670, 2017).